ACOD1 (aconitate decarboxylase 1)
Description:
Cis-aconitate decarboxylase that catalyzes production of itaconate and is involved in the inhibition of the inflammatory response. Acts as a negative regulator of the Toll-like receptors (TLRs)-mediated inflammatory innate response by stimulating the tumor necrosis factor alpha-induced protein TNFAIP3 expression via reactive oxygen species (ROS) in LPS-tolerized macrophages. Involved in antimicrobial response of innate immune cells; ACOD1-mediated itaconic acid production contributes to the antimicrobial activity of macrophages by generating itaconate, leading to alkylation of proteins, such as TFEB. Involved in antiviral response following infection by flavivirus in neurons: ACOD1-mediated itaconate production inhibits the activity of succinate dehydrogenase, generating a metabolic state in neurons that suppresses replication of viral genomes (By similarity). Plays a role in the embryo implantation (By similarity).
Synonyms: CAD; IRG1
Tractability: Small molecule: a structure with a bound ligand is known.
Gene: Protein-coding gene on chromosome 13 (76,948,511 to 76,958,638, forward strand). Ensembl gene ENSG00000102794.
Subcellular location: Mitochondrion
Subcellular location (Human Protein Atlas): Mitochondria; Nucleoplasm
Gene Ontology:
Molecular function: aconitate decarboxylase activity; protein homodimerization activity; lyase activity
Biological process: cellular response to lipopolysaccharide; defense response; positive regulation of antimicrobial humoral response; tolerance induction to lipopolysaccharide; cellular response to interferon-beta; cellular response to interleukin-1; cellular response to molecule of bacterial origin; cellular response to progesterone stimulus; cellular response to tumor necrosis factor; cellular response to type II interferon; defense response to virus; embryo implantation; negative regulation of inflammatory response; negative regulation of innate immune response; negative regulation of toll-like receptor 2 signaling pathway; negative regulation of toll-like receptor 4 signaling pathway; negative regulation of type I interferon production; positive regulation of reactive oxygen species metabolic process; cellular response to cocaine
Cellular component: mitochondrion
Genetic constraint (gnomAD): Loss-of-function variants: 8 observed, 9.32 expected, observed/expected ratio (o/e) 0.86, 90% interval 0.5 to 1.53. That is too few expected variants to judge how well the gene tolerates losing a copy. Missense variants: 499 observed, 565.29 expected, observed/expected ratio (o/e) 0.88, 90% interval 0.82 to 0.95. Synonymous variants: 170 observed, 216.7 expected, observed/expected ratio (o/e) 0.78, 90% interval 0.69 to 0.89.
Homologues: Orthologues: chimpanzee ACOD1 (96% identical), macaque ACOD1 (94% identical), dog ACOD1 (83% identical), rat Acod1 (83% identical), mouse Acod1 (82% identical), pig ACOD1 (82% identical), rabbit ACOD1 (80% identical), guinea pig ACOD1 (76% identical), tropical clawed frog acod1 (65% identical), zebrafish acod1 (56% identical).
Diseases named in the same sentence as ACOD1 in open-access papers:
ACOD1 is named in the same sentence as 114 diseases in open-access papers, as found by Europe PMC text mining. Sharing a sentence is not in itself a finding about the gene and the disease. The quoted sentences say what the papers report.
Sepsis (24 papers, 2015 to 2025). Sepsis is defined as life-threatening organ dysfunction caused by a dysregulated host response to infection. "Another role of ACOD1/IRG1 is as a negative regulator of TLR-mediated inflammatory innate responses in sepsis-associated immunosuppression." (PMID 33324576, 2020). "Aconitase decarboxylase 1 (Acod1) deficiency exacerbates hepatic lipid accumulation during sepsis." (PMID 38305778, 2024). "Therefore, given the importance of thermogenesis during sepsis and our findings that Acod1 deficiency impairs hepatic β-oxidation, we endeavored to determine if this has effects on BAT function." (PMID 38305778, 2024). "Utilizing Acod1 knockout mice that are deficient in synthesizing itaconate, we aimed to understand the metabolic role of itaconate in the liver and systemically during sepsis." (PMID 38305778, 2024). "Acod1 gene knockout mice exhibited more severe inflammatory responses and organ damage in the sepsis model, while Acod1 overexpression alleviated these pathological changes." (PMID 40586264, 2025). "One study demonstrated that Acod1-knockout (KO) mice exhibited exacerbated hepatic lipid accumulation during sepsis, improved glucose oxidation, and reduced fatty acid oxidation." (PMID 40142422, 2025). "In this mini-review, we highlight our recent finding of dopamine’s critical role in regulating aconitate decarboxylase 1 (ACOD1) in sepsis." (PMID 40703506, 2025). "Analysis of the RNAseq dataset (GSE154918) revealed that the Acod1 gene was significantly upregulated in clinical sepsis patient samples compared to healthy controls." (PMID 40586264, 2025). "In this study, we first revealed the close association between Acod1 and neutrophil NET formation in sepsis." (PMID 40586264, 2025). "To further explore the clinical significance of Acod1, we analyzed the relationship between its mRNA level and the severity of sepsis." (PMID 40586264, 2025). "Even when administered after the onset of sepsis, pramipexole significantly improved survival rates, reduced pro-inflammatory cytokine levels, attenuated organ damage, and downregulated ACOD1 and CD274 expression." (PMID 40703506, 2025). "The protective effects observed in both in vivo and in vitro sepsis models highlighted the potential of Acod1/ITA as a target for sepsis treatment." (PMID 40586264, 2025). "This inverse correlation between dopamine and ACOD1 expression in human sepsis underscores the clinical relevance of our animal studies." (PMID 40703506, 2025). "The observed association of ACOD1 and CD274 with inflammatory markers in patients further reinforces the potential role of this axis in sepsis pathogenesis." (PMID 40703506, 2025). "Our study first revealed the critical role of the Acod1/ITA axis in the immune response of neutrophils in sepsis." (PMID 40586264, 2025). "This study identified Acod1 as a potential key metabolic regulator in sepsis, with its product ITA significantly modulating the formation of neutrophil extracellular traps (NETs)." (PMID 40586264, 2025). "By analyzing the peripheral blood PBNs of clinical sepsis patients and sepsis mouse models, we found that the expression level of the Acod1 gene was significantly correlated with the formation of NETs." (PMID 40586264, 2025). "Seven days after establishing the CLP sepsis model, the survival rate of Acod1‐/‐ mice was significantly lower than that of WT mice." (PMID 40586264, 2025). "To thoroughly investigate the role of Acod1 in sepsis, we established two animal models: the CLP sepsis model and the LPS‐induced sepsis model." (PMID 40586264, 2025). "The results indicated that the Acod1/ITA signaling pathway played a crucial role in alleviating sepsis‐related inflammation and organ damage." (PMID 40586264, 2025). "The results showed that the expression level of Acod1 mRNA was significantly negatively correlated with the severity of sepsis." (PMID 40586264, 2025).
Sepsis (continued). "Acod1 induced by hemeoxygenase-1 or carbon monoxide constricts LPS-mediated sepsis and the production of pro-inflammatory cytokines." (PMID 38730297, 2024). "Utilizing Acod1 knockout mice we aimed to address the effects of itaconate on hepatic and systemic metabolism in response to polymicrobial sepsis." (PMID 38305778, 2024). "Specifically, Acod1 KO mice develop a heightened level of hepatic steatosis when induced with polymicrobial sepsis." (PMID 38305778, 2024). "Preclinical studies using animal models of acute endotoxemia identified a protective effect of ACOD1 in mitigating lethal inflammation in sepsis, identifying the importance of ACOD1 expression in the antimicrobial armory of macrophages." (PMID 39351225, 2024). "The gene encoding aconitate decarboxylase (Acod1), also known as the immune responsive gene 1 (IRG1) was strikingly induced 452-fold by sepsis in the lungs whereas the NTCI attenuated its expression to the 103-fold level over the untreated control." (PMID 37638006, 2023). "On the other hand, ACOD1 has also been reported to enhance tumour growth and reduce T-cell activity and aggravate sepsis in a mouse model." (PMID 37365251, 2023). "To determine the significance of STING1-mediated ACOD1 expression in vivo, we used two mouse models, including one for endotoxemia as well as polymicrobial sepsis induced by cecum ligation and puncture (CLP)." (PMID 35769880, 2022). "Subsequent analysis of isolated peritoneal macrophages confirmed that STING1 is required for inducible ACOD1 expression and itaconate production in the setting of experimental endotoxemia or polymicrobial sepsis." (PMID 35769880, 2022). "Accordingly, we also found that sepsis significantly induces ACOD1 and elevates itaconate in isolate hepatocyte preparations." (PMID 33616039, 2021). "In summary, Acod1/ITA enhances UBR5 enzyme activity by alkylating the Cys2768 site, which in turn promotes K48‐linked ubiquitination and degradation of PAD4, thereby regulating NETosis and providing protective effects in sepsis." (PMID 40586264, 2025). "Furthermore, we conducted a correlation analysis of the Acod1 mRNA level in the peripheral blood of sepsis patients and the levels of NETs markers." (PMID 40586264, 2025). "Furthermore, in a cecal ligation and puncture (CLP) mouse model, we demonstrated that targeting Acod1 in neutrophils effectively treated sepsis." (PMID 40586264, 2025). "We detected the expression level of Acod1 mRNA in peripheral blood neutrophils of healthy volunteers and sepsis patients, and determined the concentration of pro‐inflammatory factor TNF‐α in peripheral blood, as well as the content of NETs' characteristic components CitH3‐DNA and MPO‐DNA." (PMID 40586264, 2025). "Further investigation confirmed the impact of Acod1/ITA on sepsis and NETosis." (PMID 40586264, 2025). "Overall, these findings suggest that interventions aimed at regulating the Acod1/itaconate axis may hold potential therapeutic advantages in regulating dyslipidemia at both the local and systemic levels observed during sepsis." (PMID 38305778, 2024). "However, in a mouse study utilizing a cecal ligation-induced polymicrobial sepsis model, ACOD1 upregulation was responsible for the activation of immune pathways and sustained proinflammatory signaling through itaconate-dependent and independent mechanisms." (PMID 39351225, 2024). "Notably, the induction of the ACOD1/IRG1‐itaconate axis in monocytes contributes to the immune paralysis in sepsis, while its inhibition in macrophages reduces the tumour burden in peritoneal tumours." (PMID 35838338, 2022). "However, it remains unknown the systemic effects of Acod1 KO on sepsis-induced shifts in fuel preference." (PMID 38305778, 2024). "Further analysis showed a correlation between Acod1 gene levels and PAD4 and NE gene levels in sepsis patients." (PMID 40586264, 2025).
Sepsis (continued). "This study finds that the levels of NETs in peripheral blood are significantly elevated in clinical sepsis patients and cecal ligation and puncture (CLP) mouse models, and the expression of Acod1 is closely related to the generation of NETs." (PMID 40586264, 2025). "In a mouse model of sepsis induced by cecal ligation and puncture (CLP), global or myeloid-specific genetic knockout of either CDK2 or ACOD1 significantly improved survival, attenuating systemic inflammation, organ dysfunction, and coagulopathy." (PMID 40703506, 2025). "In conclusion, this study combines transcriptomics, metabolomics, genetic engineering, and co‐immunoprecipitation techniques to reveal the molecular mechanism of Acod1/ITA in regulating NETs, providing new potential targets and theoretical basis for the treatment of sepsis." (PMID 40586264, 2025). "By regulating the Acod1/ITA axis or the downstream UBR5‐PAD4 signaling pathway, and by using 4‐OI with good cell membrane permeability, new therapeutic strategies can be developed, which can effectively reduce the inflammatory burden of sepsis patients and improve their prognosis." (PMID 40586264, 2025). "Pharmacological inhibition of CDK2, a kinase upstream of ACOD1, with dinaciclib has replicated these benefits in CLP and other clinically relevant sepsis models (e.g., E. coli and S. pneumoniae), suggesting that targeting the CDK2-ACOD1 axis may be a promising therapeutic strategy." (PMID 40703506, 2025). "Consequently, the conditional deletion of STING1 in myeloid cells fails to produce ACOD1 and itaconate, thereby protecting mice against endotoxemia and polymicrobial sepsis." (PMID 35769880, 2022).
viral infection (17 papers, 2017 to 2026). "Inhibition of ACOD1 causes microglia forming a protective subtype and promotes neuronal regeneration after parasite or virus infection." (PMID 38644791, 2024). "LncRNA-ACOD1, which is identified by the nearby gene encoding aconitate decarboxylase 1 (Acod1), significantly attenuates viral infection by directly binding to the metabolic enzyme glutamic-oxaloacetic transaminase (GOT2) and enhancing its catalytic activity." (PMID 36604148, 2022). "In contrast, viral infection-related cytokines, such as IFNs, likely are a stimulator of ACOD1 upregulation." (PMID 35769880, 2022). "A special viral infection-induced lncRNA aconitate decarboxylase 1 (ACOD1) directly interacts with glutamic-oxaloacetic transaminase-2 (GOT2) to enhance its enzymatic activity and provide metabolites for viral replication." (PMID 32174794, 2020). "Here we found that IRF8 showed a relatively higher frequency of putative TFBSs in the promoters of genes in the cluster 3, which includes the aconitate decarboxylase 1 (ACOD1) gene whose expression can be induced by bacterial or viral infections." (PMID 31382472, 2019). "Several of the upregulated genes indicated a cellular response to viral infection (CXCL11, CCL8, DEFB103A, IFI6, ACOD1, and DEFB4A)." (PMID 38755665, 2024). "(2017) showed that lncRNA aconitate decarboxylase 1 (ACOD1) might be induced by viral infection through a pathway that is independent of interferon regulatory factor 3 (IRF3)/type I IFN (IFN‐I) signalling, but dependent on the NF‐κB‐dependent pathway." (PMID 30499165, 2019). "Thus, the production of ACOD1 in virus infection may not come directly from nucleic acid ligands." (PMID 35769880, 2022). "Although the role of Acod1 in the context of HAND has not been examined, there is a rapidly emerging recognition of the importance of its product, the metabolite itaconate, in cellular inflammatory pathways and in the progression of various viral infections." (PMID 38884890, 2024).
glioma (9 papers, 2020 to 2025). A benign or malignant brain and spinal cord tumor that arises from glial cells (astrocytes, oligodendrocytes, ependymal cells). "Similar ACOD1 protein expression patterns have been found in cancers such as human glioma, correlating with recurrence-free survival and cancer stage." (PMID 40552282, 2025). "Also, Acod1 expression increased CD14+ cells in ovarian carcinoma patients and correlated with glioma progression, two observations suggesting that the Acod1/itaconate metabolic pathway plays a pivotal role in certain types of cancers." (PMID 32724492, 2020).
colitis (8 papers, 2022 to 2025). Inflammation of the colon. "Then, we found that colitis symptoms, including weight loss, the disease activity index, and colon shortening, were worsened by the depletion of Acod1." (PMID 35457208, 2022). "To elucidate this, we established a DSS-induced colitis model with Acod1-deficient mice and then measured the mouse body weights, colon lengths, histological changes, and cytokines/chemokines in the colon." (PMID 35457208, 2022). "We herein first measured the RNA and protein levels of Acod1 in the colon to assess its association with DSS-induced colitis." (PMID 35457208, 2022). "This study aimed to investigate the role of Acod1 by utilizing an Acod1-deficient mouse model of DSS-induced colitis and, in particular, to elucidate the importance of itaconate." (PMID 35457208, 2022). "Our results suggest that Acod1 deficiency is due to a specific genetic defect in subjects with colitis, demonstrating the potential for novel therapies using 4-OI." (PMID 35457208, 2022). "However, according to our unpublished data, 4-OI had no inhibitory effect on colitis following the DSS treatment of wild-type mice, and 4-OI partially suppressed DSS-induced colitis in only Acod1-deficient mice." (PMID 35457208, 2022). "Finally, we confirmed that 4-octyl itaconate (4-OI) alleviated DSS-induced colitis in Acod1-deficient mice and decreased the expression of inflammatory cytokines and chemokines." (PMID 35457208, 2022). "In addition, 4-octyl itaconate (4-OI), a cell-permeable itaconate, was injected into Acod1-deficient mice to confirm its importance in our colitis model." (PMID 35457208, 2022). "In addition, the rapid colitis and increased inflammatory cytokine and chemokine levels were suppressed by the injection of 4-OI into Acod1-deficient mice." (PMID 35457208, 2022). "In addition, the colitis symptoms of Acod1-deficient mice were alleviated by treatment with 4-OI." (PMID 35457208, 2022). "In the present study, we verified that CEP ameliorated colitis through modulating macrophage infiltration and gut microbiota-related ACOD1 expression." (PMID 36770726, 2023). "As a result, it was confirmed that mRNA and protein of ACOD1 were upregulated in the colon of DSS-induced colitis compared to the control group." (PMID 35457208, 2022). "In the same context, Acod1 expression was herein shown to be upregulated in the colons of wild-type mice with DSS-induced colitis." (PMID 35457208, 2022). "Our data clearly showed that Acod1 deletion resulted in severe DSS-induced colitis and substantial increases in inflammatory cytokine and chemokine levels." (PMID 35457208, 2022). "Our data revealed that Acod1 deletion resulted in severe DSS-induced colitis and clearly demonstrated that the levels of inflammatory cytokines and chemokines were increased." (PMID 35457208, 2022). "Overall, these results demonstrate that Acod1 gene deletion exacerbates colon inflammation in a mouse model of colitis." (PMID 35457208, 2022). "LFD 2% male mice had higher expression of Acod1, Lcn2, and S100a9, which are upregulated in colitis and inflammatory bowel disease." (PMID 36501176, 2022). "In conclusion, these results suggest that that Acod1 deletion resulted in severe DSS-induced colitis and substantial increases in inflammatory cytokine and chemokine levels." (PMID 35457208, 2022). "Our results suggest that Acod1 may normally play an important regulatory role in the pathogenesis of colitis, demonstrating the potential for novel therapies using 4-OI." (PMID 35457208, 2022). "According to our data, although 4-OI was treated, DSS-induced colitis in ACOD1-deficient mice was not completely inhibited." (PMID 35457208, 2022). "Our data confirmed that Acod1 plays an essential role in the DSS-induced colitis model, but whether colitis is exacerbated due to the absence of the Acod1 gene or its product itaconate is unknown." (PMID 35457208, 2022).